PDX1 (pancreatic and duodenal homeobox 1)
Diseases named in the same sentence as PDX1 in open-access papers (continued):
Sharing a sentence is not in itself a finding about the gene and the disease.
MODY (47 papers, 2009 to 2026). "In humans, heterozygous PDX1 mutations are frequently associated with maturity-onset diabetes of the young type 4 (MODY4), whereas homozygous mutations typically result in neonatal diabetes mellitus (NDM)." (PMID 41153735, 2025). "Research into PDX1-MODY, a form of MODY caused by mutations in the PDX1 gene, enhances understanding of gene-specific mechanisms underlying glucose dysregulation and provides insights into possible approaches to restore normal metabolic function." (PMID 41199860, 2025). "Here, we report a large MODY family associated with a novel PDX1 variant and a second family with the pathogenic variant previously reported but not analyzed on the basis of in vitro functional analysis." (PMID 40379627, 2025). "In summary, rare heterozygous variants in NEUROD1 and PDX1 are low-penetrance causes of MODY, while those in APPL1 and WFS1 lack robust genetic evidence for causality and should not be included in MODY testing panels." (PMID 40779032, 2025). "Pancreatic and duodenal homeobox 1 (PDX1) gene is the fourth causative gene of MODY, PDX1-MODY (MODY4)." (PMID 40379627, 2025). "Additional environmental or genetic factors are clearly acting alongside PDX1 mutations in the etiology of MODY." (PMID 33795639, 2021). "Apart from Pdx1 and GK, there is another important group of mutated genes that is involved in MODY and are the hepatocyte nuclear factors (HNFs)." (PMID 34069890, 2021). "Pathogenic mutations in GCK, HNF1A, HNF1B, HNF4A, and PDX1 confirmed MODY in 7 families, giving an overall positivity rate of 22.6% in this cohort." (PMID 34373539, 2021). "MODY is a rare monogenic type of diabetes caused by heterozygous mutations of PDX1, an autosomal dominant gene that is important for regulating pancreatic function and development." (PMID 31322178, 2019). "Moreover, another variant in the same PDX1 amino acid position (p.P33T) was described as associated with MODY and shown to lead to reduced binding to the insulin promoter and decreased transcriptional activity in vitro." (PMID 39364395, 2024). "Similarly, in the case of MODY diabetes, the heterozygous MLKL loss-of-function mutation also segregated with heterozygous deleterious mutations in the known MODY gene PDX1, as well as ERN2, NIPAL4 and SPTBN4 in affected individuals." (PMID 36755069, 2023). "In conclusion, a novel mutation site of MODY type 4 in the PDX1 gene was identified in a family with MODY, which may provide a basis for its clinical treatment." (PMID 31322178, 2019). "The findings of the present study confirmed the presence of MODY4 in families caused by PDX1 gene mutation in the Chinese population, and suggested that attention should be paid to screening for MODY among diabetic patients with a strong family genetic background and onset in adolescence." (PMID 31322178, 2019). "In the present study, WES was performed on a family of three (two members with MODY and one healthy member), and a novel mutation site on the pancreatic and duodenal homeobox 1 (PDX1) gene was identified, which was subsequently verified by sequencing in relatives of the individuals." (PMID 31322178, 2019). "To do this, we chose a mouse model for maturity onset diabetes of the young (MODY4), which is caused by Pdx1 haploinsufficiency and can be modeled using Pdx1tTA/+ mice." (PMID 25144761, 2014). "Maturity-onset diabetes of the young (MODY), a monogenic form of diabetes, can result from mutations in one of the genes expressed in β-cell that include GCK, HNF1A, HNF1B, HNF4A, PDX1, and B2M." (PMID 33113859, 2020). "In India, targeted next-generation sequencing of 10 MODY genes in 56 patients identified potentially pathogenic variants in HNF4A, GCK, HNF1A, PDX1, HNF1B, NEUROD1, and PAX4 in 11 individuals, suggesting a more complex etiological spectrum in this population." (PMID 41153735, 2025).
MODY (continued). "Heterozygous variants in NEUROD1, PDX1, APPL1, and WFS1 have been implicated in MODY, but strong genetic evidence supporting causality is lacking." (PMID 40779032, 2025). "The first reported MODY-associated variants in NEUROD1, PDX1, APPL1, and WFS1 were <1:20,000 frequency." (PMID 40779032, 2025). "Third, it describes a patient carrying two predicted deleterious variants in different MODY genes (PAX4 p.Ser67Arg and PDX1 p.Gly137Cys)." (PMID 41262822, 2025). "For the CEL, PDX1, INS, KCNJ11 and ABCC8 genes, MODY is caused only by specific variants resulting in dominant‐negative/gain of function effects; null variants in these genes do not cause MODY." (PMID 35445424, 2022). "Seven out of 31 index patients (22.6%) were confirmed as MODY with variants in genes encoding GCK, HNF1A, HNF1B, HNF4A, and PDX1." (PMID 34373539, 2021). "The six major MODY-causing genes encodes hepatocyte nuclear factor 4α (HNF4α), HNF1α, glucokinase (GCK), pancreatic and duodenal homeobox 1 (PDX1), HNF1β, and neurogenic differentiation 1 (NEUROD1)." (PMID 34444990, 2021). "As a result, the mutation has the potential to weaken the transcriptional activity of PDX1, which could contribute to the development of MODY." (PMID 41199860, 2025). "Mutations in HNF1A, PDX1, and HNF1B, which affect pancreatic development, have been associated with increased risk of monogenic forms of maturity onset diabetes of the young (MODY types 3, 4, and 5) and pancreatic cancer." (PMID 40427173, 2025). "In summary, our characterization of a mouse model with the human MODY-causing PDX1P33T mutation revealed a striking divergence from the human phenotype and highlighted the importance of PDX1’s disordered regions in mediating dynamic protein-protein interactions essential for insulin expression." (PMID 41199860, 2025). "Interestingly, in this study population, utilizing the NGS we have identified MODY variants in NEUROD1, PDX1 and BLK genes in comparison to the more commonly reported HNF4A, GCK and HNF1A gene variants." (PMID 28095440, 2017). "Mutations in genes like pancreatic and duodenal homeobox 1 (PDX1, MODY4), hepatocyte nuclear factor 1 beta (HNF1B, MODY5) neurogenic differentiation 1 (NEUROD1, MODY6) and insulin (INS, MODY10) cause relatively rare forms of MODY." (PMID 26300908, 2015). "There are 14 different variants of MODY (For instance, there are mutations that affect glucokinase (GK) gene, and it is known as MODY2, or different transcription factors which are involved in the maturation of pancreatic β cells, such as pancreatic and duodenal homeobox 1 (Pdx1), known as MODY 4)." (PMID 34069890, 2021). "MODY are also associated with mutations in the genes encoding transcription factors like, hepatic nuclear factor 4 alpha (HNF4A), HNF1 homeobox A (HNF1A), pancreatic and duodenal homeobox 1 (PDX1), HNF1 homeobox B (HNF1B) and neurogenic differentiation 1 (NEUROD1)." (PMID 22399922, 2010). "In this study, we used a large clinically suspected MODY cohort and population controls to assess the genetic evidence for NEUROD1, PDX1, APPL1, and WFS1." (PMID 40779032, 2025). "Although DKA is relatively rare, there are relevant reports, observed in some types of MODY, such as INS-, PDX1-, NEUROD1-, HNF1A- and HNF1B-MODY." (PMID 40303944, 2025). "Previous studies have shown that it modulates the expression of several MODY genes, including insulin, GCK, ABCC8, PDX1, and PAX4." (PMID 40148250, 2025). "Five out of eleven MODY genes were found affected, and these were GCK, HNF1B, HNF4A, PDX1, and RFX6." (PMID 39364395, 2024). "Another type of MODY is MODY4 (PDX1), The PDX1 gene is involved in insulin gene transcription regulation." (PMID 34763692, 2021). "To date, 14 disease genes for MODY are identified; most of them are transcription factors MODY1 (HNF4A), MODY3 (HNF1A), MODY4 (PDX1), MODY5 (HNF1B), MODY6 (NEUROD1/BETA2), MODY7 (KLF11), MODY8 (CEL), MODY9 (PAX4), MODY11 (BLK), and MODY14 (APPL1)." (PMID 31145732, 2019).
MODY (continued). "In conclusion, we provide genetic evidence that NEUROD1 and PDX1 cause low penetrance MODY whereas variants in APPL1 and WFS1 do not cause MODY and should not be included in MODY genetic analysis." (PMID 40779032, 2025). "In all cases, we observed consistent results that APPL1 and WFS1 variants are not enriched in the MODY cohort, whereas NEUROD1 and PDX1 were at a level similar to RFX6." (PMID 40779032, 2025).
insulinoma (45 papers, 2008 to 2025). "To test the role of ARC in the development of insulinomas, we bred Pdx1-Cre; Men1 f/f mice with mice in which the gene encoding ARC had been deleted in the germ line to create mice lacking both menin and ARC in all cells of the pancreas." (PMID 26709830, 2015). "Using pMAGIC-derived Ad5 vectors, we demonstrate that Sa-dCas9/LSD1-mediated epigenetic modification of the Area IV element causes a significant inhibition of endogenous PDX1 expression in both the INS1 832/13 rat insulinoma cell line and in primary rat pancreatic islets." (PMID 30590691, 2019). "Here, we also employed Pdx1-cre to activate T antigen and observed pancreatic ductal adenocarcinoma and insulinoma." (PMID 37247123, 2023). "Previous studies demonstrated that knockdown of Pdx1 in rat insulinoma cells (INS-1) results in a reduced SERCA2b expression and decreased ER Ca2+ levels." (PMID 36574297, 2023). "Pancreatic insulinoma and ductal adenocarcinoma, gastric adenoma, and duodenal cancer were detected in Pdx1-cre/T antigen mice." (PMID 37247123, 2023). "The incidences of gastric adenoma, and pancreatic and duodenal adenocarcinoma were 100% (15/15) in Pdx1-cre/T antigen mice, and the incidence of insulinoma was 16.7% (3/18) at the age of 2–5 months." (PMID 37247123, 2023). "Specifically, while the expression of PDX1 is particular for low grade and benign tumors, mainly insulinomas, ARX expression is specific to advanced stages." (PMID 36139607, 2022). "Further, siRNA knockdown of PDX1 in an insulinoma cell line led to reduced promoter occupancy of p300." (PMID 36272648, 2022). "Transfection of a small interfering RNA specific for Pdx1 in pancreatic islets insulinoma cell line shows that Pdx1 directly regulates the insulin transcription promotor." (PMID 34177802, 2021). "PDX1 expression was observed in 34/35 primary insulinomas (97%), and 2/3 liver metastases; in contrast, only 3/35 (9%) of primary insulinomas were ARX positive, while all liver metastases were ARX positive." (PMID 32103422, 2020). "Beta-like and/or PDX1 positive tumours are strongly enriched for benign insulinomas in both the first and second cohort." (PMID 33288854, 2020). "Only for the intermediate-ADM insulinoma, data on PDX1 and ARX were available; it resulted positive for ARX, and negative for PDX1 expression." (PMID 33288854, 2020). "A multi-parameter, high-content screening study reported that seven extracts, from a library of 1319 marine invertebrate extracts, reproducibly altered the promoter activity of insulin and/or PDX-1 in murine Min6 insulinoma pancreatic β-cells." (PMID 32847055, 2020). "While the vast majority of β-like PanNETs expressed PDX1 and insulin, the two malignant (N1 and/or M1) insulinomas of our cohort, showed one intermediate-ADM (DAXX/ATRX mutated) and one α-like (DAXX/ATRX wild-type) methylation signatures." (PMID 33288854, 2020). "To demonstrate this, we used pMAGIC to target Sa-dCas9/LSD1 and modify the epigenetic status of a conserved enhancer, resulting in altered expression of the homeobox transcription factor PDX1 and its target genes in pancreatic islets and insulinoma cells." (PMID 30590691, 2019). "Taken together, these results implicate epigenetic modification of Area IV as a significant modulatory event for control of PDX1 expression in this rodent insulinoma cell line model." (PMID 30590691, 2019). "In other mouse models of PanNETs21,24,25, MEN1 deletion using the insulin or PDX1 promoter driven Cre construct, insulinomas, glucagon-expressing tumors and well differentiated PanNETs were also observed." (PMID 30315258, 2018).
insulinoma (continued). "This approach was applied to insert a green fluorescent protein (GFP) coding sequence (CDS) into the genomic locus of the pancreatic and duodenal homeobox 1 (Pdx1) gene in the mouse insulinoma cell line (MIN6) and mouse embryonic stem cells (ESCs)." (PMID 28042537, 2017). "We have used insulinoma MIN6 cells which constantly express Pdx1, for convenient detection of knock-in events." (PMID 28042537, 2017). "Knockdown of Pdx1 gene expression in mouse MIN6 insulinoma cells induced apoptotic cell death with an increase in Bax activation and knockdown of Bax reduced apoptotic β-cell death." (PMID 27137932, 2016). "The SSTR1/5−/− mouse model was used as the mice represent an immune-competent insulinoma-like mouse model with overexpression of PDX-1 in both acinar cells and islet cells, featured with hyperinsulinemia and hypoglycemia." (PMID 22905092, 2012). "PDX-1 also was overexpressed in mouse insulinoma (β TC-6) cells and in both islet and acinar cells of the pancreata of somatostatin receptor subtypes 1 and 5 knock-out mice (SSTR1/5−/−) (respectively) as compared to that of wild type mice." (PMID 22905092, 2012). "Glucose-regulated interactions between Hdac1/2, Pdx1 and/or Sox6 have been suggested to control insulin gene expression in mouse insulinoma cell lines." (PMID 18687323, 2008). "It is noteworthy that all insulinomas were PDX1-positive and, thus, belonged to B-type NETs." (PMID 39456803, 2024). "PDX1-high tumors mainly comprised insulinomas and showed high similarity to pancreatic beta cells." (PMID 39456803, 2024). "Typical insulinomas resemble to β-cells with high expression of PDX1 and a good prognosis." (PMID 36139607, 2022). "For instance, quercetin can improve insulin production by rat insulinoma INS-1 cells in response to high glucose, as well as downregulate the relative expression levels of pro-apoptotic Bax and PDX-1 mRNAs, inhibit oxidative stress caused by H2O2, and reduce INS-1 cell apoptosis." (PMID 34824300, 2021). "Therefore, we determined ARX and PDX1 expression in a cohort of 35 sporadic primary insulinomas and two liver metastases of inoperable primary insulinomas." (PMID 32103422, 2020). "Moreover, PDX-1 has been shown to be a potential therapeutic target for pancreatic cancer, insulinoma and islet neoplasia." (PMID 24705209, 2013). "Moreover, the expression of PDX1 itself is reduced in insulinomas." (PMID 33060578, 2020). "In addition to its anti-inflammatory action, we noted that LXA4 increased the expression of PDX1 in RIN (rat insulinoma) cells in vitro (PDX1 is a homeobox protein expressed in β pancreatic cells that maintains and expresses the endocrine function of the pancreas) (unpublished data)." (PMID 28824543, 2017). "Moreover, overexpression of Pdx1 eliminated glucagon mRNA and protein and promoted the expression of β-cell specific genes, while induction of dominant-negative Pdx1 resulted in differentiation of β-cells into α-cells in the rat insulinoma cell line." (PMID 26845333, 2016).
insulinoma (continued). "It is worth noting that in another study, three metastatic insulinomas were included and exclusively displayed positivity for ARX (>10% of cells) and ALT, indicating that PDX1 and ARX expression are merely partially bound to hormonal activity." (PMID 39456803, 2024). "Consistent with Pdx1-CreER expression in pancreatic β-cells, the MAP model developed PanNET insulinomas (see insulin expression." (PMID 38609433, 2024). "The same study reported cooperativity between MafA, PDX1, and E47/β2 toward INS activation in rat and mouse insulinoma cell lines." (PMID 36272648, 2022). "Next REST was overexpressed in the mouse insulinoma cell line MIN6 and gene expression was analysed by qPCR for Rest, Ins2, Pdx1, Snap25 and Scrt1 three days post infection." (PMID 33888791, 2021). "Only hypermethylated PDX1 and NKX3-1 binding sites in insulinomas mapped to islet-specific enhancers (7/14), and the majority of these (4/7) were near the INS/IGF2 locus." (PMID 33060578, 2020). "This begs the question, “if PDX1 and other canonical beta-cell transcription factors cannot access and drive INS gene expression in insulinoma, what does drive INS gene expression?”." (PMID 33060578, 2020). "Taken together, these observations most likely reflect the incidental inclusion of NKX3-1 in this analysis and suggest that PDX1 and NFATC1 binding sites as the key targets of the differential methylation of insulinomas." (PMID 33060578, 2020). "In βTC3 insulinoma cells this phosphorylation is induced upon a stimulus with glucagon like peptide GLP1 and acts as a positive regulator of PDX-1." (PMID 28036027, 2016). "Recent studies show that RPL-1980 abolishes GLP-1-stimulated PDX-1 expression in mouse insulinoma β-TC6 cells, indicating that SSTR5-mediated somatostatin signaling is a potential novel negative regulator for PDX-1 expression." (PMID 25009500, 2014). "We report here that overexpression of Notch1 intracellular domain (NICD), an activated form of Notch1, enhanced PDX-1 expression in both PDX-1 stable HEK293 cells and mouse insulinoma β-TC-6 cells, while NICD shRNA inhibited the enhancing effect." (PMID 24705209, 2013). "In rat insulinoma RIN 1046-38 cells, expression of Pdx1 is increased upon treatment with GLP-1, forskolin or 8-Bromo-cAMP, and inhibition of PKA, or antagonism of cAMP, inhibits GLP-1-stimulation of Pdx1 expression." (PMID 40024571, 2025). "This strongly suggests distinct endocrine (de)differentiation in aggressive insulinomas versus small and indolent insulinomas, with similarities of aggressive insulinomas to non-functional PanNETs which often co-express ARX/PDX1." (PMID 39331358, 2024). "PDX1 staining positive was commonly found in non-metastatic insulinomas, while ARX staining positive was preferred in a portion of NF-PanNETs." (PMID 37251916, 2023). "Previous studies have shown that non-metastatic insulinomas exclusively expresses PDX1, whereas liver metastatic foci and metastatic insulinoma are more likely to express ARX." (PMID 37251916, 2023). "Menin knockdown concomitantly decreased the mRNA expression of both MAFA and β-cell differentiation markers (INS, GCK, SLC2A2, and PDX1) while increasing tumor proliferation, indicating that altered menin expression disrupts the MAFA differentiation pathway in insulinoma." (PMID 35406570, 2022). "Additionally, INS1e rat beta-cell-like insulinoma cells and human islets chronically exposed to high glucose display GSK3-mediated phosphorylation of PDX1 serine 268, resulting in PDX1 degradation and reduced expression of PDX1 target genes." (PMID 36187092, 2022). "The two subgroups appear to have a distinct molecular profile.; specifically, subgroup A as NF-PanNETs with noticeably worse outcome, while subgroup B, represented by insulinomas, have a good prognosis and are usually not methylated at the PDX1 promoter." (PMID 36139607, 2022).